EGF (epidermal growth factor)
Diseases named in the same sentence as EGF in open-access papers (continued):
Sharing a sentence is not in itself a finding about the gene and the disease.
Pca (1 paper, 2018). "in vitro, some studies have found that both interleukin-6 (IL-6) and epidermal growth factor (EGF) can activate Akt and its pathway to promote Pca progression." (PMID 29416748, 2018).
peritonsillar abscess (1 paper, 2018). An abscess that develops in the space surrounding one or both palatine tonsils. "Salivary EGF concentrations were found to be significantly lower in patients with aphthous stomatitis or peritonsillar abscess and decreased even after healing and in the absence of these lesions." (PMID 29657585, 2018). "Although the detailed mechanisms by which EGF secretion into the saliva is controlled are not yet known, several studies have found that salivary EGF levels are significantly decreased in patients with intraoral inflammatory lesions, such as aphthous stomatitis and peritonsillar abscess." (PMID 29657585, 2018).
pharyngitis (1 paper, 2020). Inflammation of the throat most often caused by viral and bacterial infections. "DC, CC, and BC analysis indicated that ALB (serum albumin), PPARγ (peroxisome proliferator-activated receptor gamma), MAPK3 (mitogen-activated protein kinase 3), EGF (epidermal growth factor), and PTGS2 (prostaglandin G/H synthase 2) are closely related to pharyngitis." (PMID 33101439, 2020).
placental diseases (1 paper, 2021). "In addition, aberrant expressions of EGF and EGFR are associated with trophoblast cell invasion-related placental diseases." (PMID 34620174, 2021).
pleural mesothelioma (1 paper, 2025). A neoplasm that arises from the mesothelial cells of the pleura. "Additionally, fibroblast growth factor 2 (FGF2) and epidermal growth factor (EGF) can promote a fibroblast-like phenotype with invasive traits and reduced cell adhesion in pleural mesothelioma." (PMID 40506895, 2025).
pneumococcal infection (1 paper, 2023). Infections with bacteria of the species streptococcus pneumoniae. "Our previous study showed that NE activity increased to an average of 431.6 mU/ml in BALF of pneumococcal-infected mice, suggesting that increased NE activity because of pneumococcal infection may degrade not only EGFR but also EGF and inhibit alveolar epithelial repair." (PMID 37119853, 2023).
Premature rupture of membranes (1 paper, 2022). Premature rupture of membranes (PROM) is a condition which occurs in pregnancy when the amniotic sac ruptures more than an hour before the onset of labor. "Shobokshi previously reported elevated EGF concentrations in cases of premature rupture of membranes (PROM) with intraamniotic infection." (PMID 35328399, 2022).
proliferative vitreoretinopathy (1 paper, 2010). Vitreoretinal membrane shrinkage or contraction secondary to the proliferation of primarily retinal pigment epithelial cells and glial cells, particularly fibrous astrocytes, followed by membrane formation. "Further research into the role of GlcN as a potential agent for the prevention and treatment of RPE-mediated ocular proliferative disorders, such as proliferative vitreoretinopathy, and other EGF-dependent proliferative cell-growth disorders, is warranted." (PMID 21151603, 2010).
pulmonary edema (1 paper, 2012). Accumulation of fluid in the lung tissues causing disturbance of the gas exchange that may lead to respiratory failure. "The W/D value decreased significantly 24 h after EGF treatment, due to pulmonary edema, with a certain degree of ease." (PMID 23170113, 2012).
retinal diseases (1 paper, 2021). "Since the RPE is primarily or secondarily involved in the course of several retinal diseases such as AMD and retinitis pigmentosa, the intravitreally applied EGF and its family members may theoretically have an influence on the course of such diseases." (PMID 33713254, 2021).
Salmonella Infections (1 paper, 2010). Infections with bacteria of the genus SALMONELLA. "Next, we examined the biological effect of Salmonella infection expression on epithelial proliferation, which is regulated by multiple pathways, including the Akt and EGF pathways." (PMID 21172007, 2010).
Senile Vaginitis (1 paper, 2022). "In this experiment, genistein could enhance the expression of EGF and E-cadherin to promote the proliferation of vaginal epithelial cells and repair the vaginal wall, which improved the symptoms of senile vaginitis and had a better therapeutic effect on senile vaginitis." (PMID 35458584, 2022).
serous cystadenocarcinoma (1 paper, 2013). A malignant serous cystic neoplasm usually involving the ovary or the pancreas. "As a result, it is also theorized that EGF may affect effective claudin-4 targeting therapy with CPE in serous cystadenocarcinoma." (PMID 23685873, 2013).
skin changes (1 paper, 2022). "The mean level of serum EGF was 85.2±96.2 pg/ml for people with grade 2 changes, in contrast to 67.2±48.7 pg/ml for those with grade 6 skin changes." (PMID 35045077, 2022).
skin infection (1 paper, 2023). An inflammatory process affecting the skin, caused by bacteria, viruses, parasites, or fungi. "For instance, inhibition of EGFR affects tissues normally dependent on EGF signals, causing skin dryness, acneiform rashes, and skin infections." (PMID 37686523, 2023).
Skin ulcer (1 paper, 2015). A discontinuity of the skin exhibiting complete loss of the epidermis and often portions of the dermis and even subcutaneous fat. "On the other hand, EGF has recently been used in components for the treatment of intractable skin ulcers and burn ulcers utilizing its capacity to induce proliferation of skin epidermis." (PMID 26173062, 2015).
spinal cord injury (1 paper, 2025). Penetrating and non-penetrating injuries to the spinal cord resulting from traumatic external forces (e.g., WOUNDS, GUNSHOT; WHIPLASH INJURIES; etc.). "As a member of the epidermal growth factor (EGF) family, TGFα induces astrocyte proliferation and increases neuronal survival, migration and axonal growth in multiple contexts, including models of spinal cord injury (SCI) and ischemic stroke." (PMID 40537468, 2025).
stenosis (1 paper, 2024). "In a similar study, the role of EGF was investigated in CEB, and the study revealed that collagen synthesis was significantly higher in the EGF-treated group than in collagen synthesis of the untreated group on the 5th postoperative day with a lower esophageal stenosis index in the CEB + EGF group." (PMID 38392220, 2024).
systemic inflammatory response syndrome (1 paper, 2026). SIRS is a serious condition related to systemic inflammation, organ dysfunction, and organ failure. "Regarding EGF, its administration attenuated lung inflammation and injury, probably through activating EGFR, leading to the suppression of NF-κB signaling, promotion of cell proliferation, and inhibition of apoptosis, as well as the prevention of systemic inflammatory response syndrome." (PMID 41596232, 2026).
T-cell lymphoma (1 paper, 2025). "Compared to T-cell lymphoma without PEH, skin T-cell lymphoma accompanied by PEH exhibited stronger expression of EGF and TGF-α on T cells and EGFR on epidermal cells." (PMID 40666517, 2025).
tenosynovitis (1 paper, 2025). Inflammation of the synovial lining of a tendon sheath. "Despite this, no prior study has concurrently tracked VEGF, PDGF-AB, EGF, and TGF-β kinetics beyond 7 days post-PRP using standardized protocols in tenosynovitis." (PMID 41327174, 2025).
testicular cancer (1 paper, 2025). A primary or metastatic malignant neoplasm that affects the testis. "An analysis of co-expression of proteins in the hormonal clusters #1 and #3 of TCGA testicular cancers underline the relevance of EGF/ERBB, MAPK and AKT/mTOR signaling pathways, whose members were identified as prominent hubs of communities of co-regulated proteins." (PMID 40011822, 2025).
thrombophilia (1 paper, 2019). A condition characterized by an abnormally high level of thrombi. "This study focused on FXII as a growth factor and indicated that autoantibodies in patients with recurrent pregnancy loss may not only cause thrombophilia-associated complications but may also disrupt the EGF system." (PMID 31489398, 2019).
thymic lymphoma (1 paper, 2019). "Further, EGF-dependent EGR1 upregulation inhibits the growth of thymic lymphoma by suppressing MMP9 production from stromal cells." (PMID 30845713, 2019).
tongue tumors (1 paper, 2017). "We did find that ligand concentrations in tongue tumors can be slightly higher than in flank xenografts, probably, because of the tumor proximity to submandibular glands, the main site of mouse EGF synthesis." (PMID 29268862, 2017). "A similar localization pattern for EGF-Rh:EGFR-GFP complexes was observed in tongue tumors, although a lower number of EGF-Rh-labeled cells was detected, probably, due to a strong autofluorescence of muscle cells in the red channel interfering with the detection of weak endosomal EGF-Rh signals." (PMID 29268862, 2017). "EGF-Rh could be detected in flank and tongue tumor xenografts ~1 hr after tail vein injection." (PMID 29268862, 2017).
tuberous sclerosis (1 paper, 2025). Hereditary disease characterized by seizures, intellectual disability, developmental delay, and skin and ocular lesions. "Here, we report that endosomal-localized EGFR/Ezrin complex interacts with and triggers the inhibition of the Tuberous Sclerosis Complex (TSC complex) in response to EGF stimuli." (PMID 39937579, 2025).
Ureteral obstruction (1 paper, 2014). Obstruction of the flow of urine through the ureter. "Notably, ureteral obstruction determines a significant increase in monocyte chemotactic protein-1 (MCP-1) expression and a decrease in epidermal growth factor (EGF) expression by tubular cells." (PMID 25101270, 2014).
urinary system cancer (1 paper, 2014). "Indeed, EGF/EGFR, FGFR2, KLK3, and PDGFRB were reported to play important roles in urinary system cancer development and progression." (PMID 24801713, 2014).
uterine cancer (1 paper, 2020). Primary or metastatic malignant neoplasm involving the uterine corpus and/or the cervix. "Studies have shown that EGF can reduce the expression of E-cadherin and enhance the occurrence of EMT in uterine cancer cells." (PMID 32148496, 2020).
uveal melanoma (1 paper, 2025). A melanoma derived from melanocytes of the uveal tract. "The overexpression of EGF or dysregulation of its receptor (EGFR) pathway has been implicated in the progression of many cancers, including uveal melanoma." (PMID 40004863, 2025).
uveitis (1 paper, 2022). An inflammatory process affecting a part of or the entire uvea. "The levels of EGF, fractalkine, IL1-β, IL-17A, IL-1RA, IL-2, IL-23, IL-8, IP-10, TNF-α and IL-6 in patients with uveitis in their active phase were independent to their counterpart levels in plasma, the difference being statistically significant (p < 0.05)." (PMID 36498608, 2022). "The levels of EGF, fractalkine, IL1-β, IL-17A, IL-1RA, IL-2, IL-23, IL-8, IP-10, TNF-α and IL-6 in patients with uveitis in their active phase were independent of their counterpart levels in plasma, the difference being statistically significant (p < 0.05)." (PMID 36498608, 2022).
varicocele (1 paper, 2025). A condition characterized by the dilated tortuous veins of the spermatic cord with a marked left-sided predominance. "The results indicated while the levels of EGF and TGF-Semen plasma β increased in varicocele patients, seminal parameters decreased in this group." (PMID 40524181, 2025).
Vertigo (1 paper, 2021). An abnormal sensation of spinning while the body is actually stationary. "No severe EGF-related complications, such as pain, severe vertigo, infection, or hyperplasia of the EAC, were observed during the treatment process." (PMID 31395492, 2021).
vesico-ureteral reflux (1 paper, 2017). "The aim of this study was to investigate the urinary concentration of epidermal growth factor (EGF) and monocyte chemotactic protein-1 (MCP-1) as reflux nephropathy (RN) biomarkers before and after endoscopic treatment of moderate to severe vesico-ureteral reflux (VUR)." (PMID 28191787, 2017).
Werner syndrome (1 paper, 2020). "Fibulin-3 was first described in 1995 as a protein containing epidermal growth factor (EGF)-like domains encoded by an mRNA transcript termed S1-5 that is overexpressed in human Werner syndrome fibroblasts, an inherited condition of early aging characterised by premature cellular senescence." (PMID 32911658, 2020).
tumor (2,494 papers, 1987 to 2026). "Communication analysis showed that compared with the low-risk tumor cell group, EGF pathway was significantly enriched in high-risk tumor cell populations." (PMID 40533802, 2025). "One approach to the cultivation of cells as microspheres to prevent the loss of tumor heterogeneity is to use serum-free medium containing basic fibroblast growth factor (bFGF), epidermal growth factor (EGF), and a neuronal viability supplement (B27 or NS-21)." (PMID 38393158, 2024). "TAMs foster tumor cell growth and angiogenesis by secreting associated growth factors such as transforming growth factor‐β, epidermal growth factor (EGF), and VEGF." (PMID 38576456, 2024). "Often associated with tumor development in mammals, the EGF pathway interacts with cell differentiation and cell fate-determining signaling pathways, such as PI3K/Akt, mitogen-activated protein kinase and Jak/Stat." (PMID 38862239, 2024). "In ovarian cancer, LINC01089 is downregulated by M2-like tumor-associated macrophages (TAMs) secreting EGF, which activates the EGFR-ERK signaling pathway." (PMID 39334363, 2024). "These cytokines contribute to preventing tumor cells apoptosis and indirectly inhibit their destruction by promoting tumor-associated macrophages (TAM) to secrete EGF, a relevant growth factor implicated in tumoral development in many patients." (PMID 38557942, 2024). "EGF secreted by tumor cells promoted an M2 polarization of tumor-associated macrophages (TAMs), associated with the suppression of cytotoxic T cell function." (PMID 38001917, 2023). "In LSCC, NOTCH1 acts as a tumor suppressor gene, and most of the mutations are loss-of-function mutations of the epidermal growth factor (EGF)-like ligand or the NOTCH intracellular domain (NICD)." (PMID 37629093, 2023). "A mechanism connecting N-linked glycosylation of PD-L1 to cancer growth and anti-tumor T cell responses was also described in a syngeneic model system of EGF-induced responses." (PMID 37830552, 2023). "Magnolin, a natural chemical present in Magnolia flos, inhibits cell proliferation caused by tumor promoters such as EGF (epidermal growth factor) and focuses on ERK1 and ERK2." (PMID 35941592, 2022). "The combined depletion of MAP4K4 and STRN3 in DAOY cells caused a dramatic reduction of tumor area, both under basal condition and under EGF stimulation." (PMID 35941177, 2022). "In turn, CAFs activated by ITGA5-overexpressing tumor cells secrete TGFβ-associated factors EGF, IP-10, IGFBP-3, BDNF, Flt-3 LG, FGF-7, IL-12, MIF and leptin." (PMID 35682890, 2022). "This expression causes the reduction of epidermal growth factor (EGF) expression that finally abrogates cell growth and tumor recurrence." (PMID 36479071, 2022). "EGF is implicated in cancer: its tyrosine kinase activity is responsible for tumour survival, growth and metastatization." (PMID 34955078, 2022). "IL-4 produced by CD-25+ Th2 tumor-infiltrating cells transforms tumor-associated macrophages into producing high epidermal growth factor (EGF) levels, promoting metastasis." (PMID 35884974, 2022). "Signaling via epidermal growth factor (EGF) leads to tumor cell proliferation, migration, and invasion by causing dimerization of EGFR, a receptor tyrosine kinase." (PMID 35456655, 2022). "Somatic mutation is followed by the clonal expansion of the tumor cell, which is frequently supported by GFs such as EGF and IGF-I." (PMID 35158804, 2022). "These EMT-TFs are induced by extracellular stimuli, including TGF-β and EGF, and by paracrine or autocrine signaling through Notch ligand and Wnt, as well as by the hypoxic tumor microenvironment and interactions with tumor-associated stroma." (PMID 35803962, 2022). "Depletion of STRN3 caused compaction of the tumor cell spheroids and prevented tissue invasion also under EGF-stimulation." (PMID 35941177, 2022).
tumor (continued). "Although non-significant given the limited sample sizes, there seems to be some evidence for an association between serum EGF and tumour size (p = 0.077)." (PMID 34115785, 2021). "In another study, migration and intravasation of tumor cells was induced by tumor-associated macrophages producing EGF." (PMID 33673054, 2021). "Other clinical and tumor characteristics have been associated with longer survival after CIMAvax-EGF." (PMID 34211836, 2021). "There are several rationales for this difference, including the prevalence of de novo T790M resistance mutation, tumor heterogeneity, difference in protein structure, and EGF‐induced tyrosine phosphorylation patterns." (PMID 34587359, 2021). "This further implies that MMP activity is mandatory for BM disruption under limited EGF conditions and triggered by tumour-associated substrate stiffening." (PMID 33921304, 2021). "AKT has many upstream signals, among which EGF/EGFR is one signal that is closely associated with tumor progression." (PMID 34069970, 2021). "Epidermal growth factor (EGF)/EGFR signaling has been implicated in many steps in the processes of tumor invasion and metastasis." (PMID 34163029, 2021). "Highly dynamic EMT was described during tumor cell intravasation stimulated by tumor-associated macrophages that produced EGF and thereby activated migration of tumor cells." (PMID 32121325, 2020). "M2 macrophage-like tumor-associated macrophages (TAMs) secreted EGF and then activated EGFR on tumor cells, further up-regulating VEGF/VEGF-R signaling in surrounding tumor cells to finally mediate OC cell proliferation and migration." (PMID 32716025, 2020). "It has been already shown that tumor-associated macrophages release tumor-derived CSF-1 and macrophage-derived EGF through a paracrine manner, further promoting therapy resistance." (PMID 33262705, 2020). "They combined these results with sequencing data to illustrate that the synergistic effect of mutations in RAS/MAPK and PI3K pathways led to EGF independent growth of tumor organoids." (PMID 33327663, 2020). "Surprisingly, of all the potential RASGAPs, we identified that only the loss of NF1 resulted in increased tumor growth and EGF-independent cell survival." (PMID 30858928, 2019). "Activation of ERK/MAPK pathways is a key event in cell proliferation and tumor progression, that occurs downstream of pathways associated with several growth factors including EGF, PDGF, VEGF, FGF, and insulin, etc.." (PMID 30651129, 2019). "Together, using patient-derived CRC organoids, we reveal that of all RASGAPs with functional GAP domains, only NF1 deficiency promote cell survival and enhanced tumor growth upon challenging EGF signaling conditions in human CRC samples." (PMID 30858928, 2019). "To our knowledge we are the first to present direct loss-of-function data that of all RASGAPs only the loss of NF1 promotes enhanced tumor growth and EGF-independent survival in CRC." (PMID 30858928, 2019). "Several molecules, including IL-10, IL-32, epidermal growth factor and growth arrest-specific gene 6, have been associated to the tumour-promoting function of TAMs." (PMID 31480312, 2019). "To investigate the molecular mechanism that underlies increased tumor growth and EGF-independent survival upon loss of NF1 expression, we analyzed the activity of the RAS-MAPK signaling pathway." (PMID 30858928, 2019). "M2 are activated by cancer cells through IL-4, IL-10, and IL-13 production and secrete macrophage-derived EGF causing tumor cell migration around blood vessels." (PMID 30662458, 2018). "CARMA3 suppression in these cells was associated with an increase in cancer cell apoptosis, a loss of EGF-induced migration, and decreased tumor growth in a mouse xenograft tumor model." (PMID 30158935, 2018).